MIR558 (microRNA 558)
Synonyms: hsa-mir-558; MIRN558
Gene: MicroRNA gene on chromosome 2 (32,532,153 to 32,532,246, forward strand). Ensembl gene ENSG00000207653.
Gene Ontology:
Biological process: miRNA-mediated post-transcriptional gene silencing
Cellular component: RISC complex